PTX3 (pentraxin 3)
Diseases named in the same sentence as PTX3 in open-access papers (continued):
Sharing a sentence is not in itself a finding about the gene and the disease.
gestational diabetes (6 papers, 2016 to 2024). Carbohydrate intolerance first diagnosed during pregnancy. "In studies with patients suffering from gestational diabetes, a connection is suspected between PTX3 and the pathophysiology of GDM." (PMID 36574434, 2022).
head and neck squamous cell carcinoma (6 papers, 2017 to 2025). A squamous cell carcinoma that arises from any of the following anatomic sites: lip and oral cavity, nasal cavity, paranasal sinuses, pharynx, larynx, and salivary glands. "At the same time, the production of PTX3 promotes the upregulation of epidermal growth factor (EGF) in head and neck squamous cell carcinoma cells, tumor cell migration, invasion and EGF-mediated metastasis." (PMID 33952272, 2021). "In this study, we found that oleate induced PTX3 expression and secretion through the activation of Akt/NF-κB pathway in head and neck squamous cell carcinomas (HNSCCs)." (PMID 28489600, 2017). "However, PTX3 has a protective effect against cancer and has been found to correlate with tumor invasion and metastasis in head and neck squamous cell carcinoma, cervical cancer, and other cancers." (PMID 35855654, 2022). "PTX3 enhances EGF-induced migration, invasion, and metastasis in head and neck squamous cell carcinoma cells." (PMID 41373493, 2025). "Inhibition of PTX3 has been shown to downregulate EMT-related molecules, such as vimentin and matrix metalloproteinase (MMP) 3, in head and neck squamous cell carcinoma cell lines." (PMID 39594709, 2024).
influenza (6 papers, 2012 to 2024). An acute viral infection of the respiratory tract, occurring in isolated cases, in epidemics, or in pandemics; it is caused by serologically different strains of viruses (influenzaviruses) designated A, B, and C, has a 3-day incubation period, and usually lasts for 3 to 10 days. "In contrast to its immune-enhancing role, deglycosylation of PTX3 during influenza infection abolishes its anti-viral activity." (PMID 30774632, 2019). "While most of investigators utilized individual serum factors such as SP-D, SP-A, MBL or PTX-3 to study influenza innate immunity, serum factors are likely to work together to exert their anti-influenza activities." (PMID 22563489, 2012). "Cerebral TB (n = 1, PTX3 <3.2 pg/ml), S. mitis endocarditis with septic embolies (n = 1, PTX3 4.9 pg/ml), neurosyphilis (n = 1, PTX3 <3.2 pg/ml), HIV (n = 1, PTX3 <3,2 pg/ml), influenza (n = 1, PTX3 <3.2 pg/ml) and EBV radiculitis (n = 1, PTX3 <3.2 pg/ml)." (PMID 36862691, 2023). "While influenza cases were primarily characterized by pro-inflammatory signaling and classical anti-viral response gene expression (e.g., BCL6, DLL4, GDF15, PTX3,HMGB2, and IL-8)." (PMID 36371548, 2023). "The long chain pentraxin, PTX3 inhibits several strains of seasonal influenza A(H1N1), A(H3N2) and influenza B viruses, though the susceptibility to PTX3 may be strain-specific as some seasonal human influenza isolates including PR8 virus and the H1N1pdm viruses are resistant to PTX3." (PMID 22563489, 2012). "Incubation of influenza-infected BALF with neutrophils did not significantly alter the gene expression of cathelicidin, S100A8, S100A9, lactotransferrin, pentraxin-3, and MMP9 (data not shown)." (PMID 23467809, 2013).
Kawasaki disease (6 papers, 2016 to 2026). A rare inflammatory disease characterized by an acute febrile, systemic, self-limiting, medium-vessel vasculitis primarily affecting children. "PTX-3, coronary artery z-scores, and clinical assessment of inflammation throughout Kawasaki disease (KD) progression in patients with normal coronary arteries (NCA) and in patients who develop coronary artery lesions (CAL)." (PMID 32670996, 2020). "PTX-3, coronary artery z-scores, and clinical assessment of inflammation throughout Kawasaki disease (KD) progression." (PMID 32670996, 2020). "Coronary artery z-scores, PTX-3 levels, and absolute neutrophil counts (ANC) throughout Kawasaki disease (KD) progression." (PMID 32670996, 2020).
meningococcal disease (6 papers, 2011 to 2025). "Elevated plasma levels of PTX3 were found in the dengue virus infection and also in the severe meningococcal disease." (PMID 27403446, 2016). "In the present study, prompted by the finding of high levels of PTX3 during meningococcal infection in humans and induction by adjuvants, we focused on the possible interaction of PTX3 with Nm." (PMID 25786110, 2015). "In patients with meningococcal disease, high PTX3 and low CRP concentration at admission discriminated between presence and absence of shock." (PMID 25530683, 2014). "High PTX3 has been found to be an early indicator of shock in severe meningococcal diseases." (PMID 23341967, 2013). "High PTX3 has also been found to be an early indicator of shock in severe meningococcal disease." (PMID 23341967, 2013). "Previous study in meningococcal disease has suggested that PTX3 may already peak during the first hours after hospital admission, this reflecting disease severity, which may suggest its utility as an early marker." (PMID 21423699, 2011).
myocardial ischemia (6 papers, 2013 to 2025). A disorder of cardiac function caused by insufficient blood flow to the muscle tissue of the heart. "Elevated PTX-3 levels correlate with the extent and severity of myocardial ischemia and infarction." (PMID 39941683, 2025). "Taken together, although PTX3 expression was extracellular in a mouse model of acute myocardial ischemia, we clearly showed by immunohistochemical staining that PTX3 expression was observed in cardiac fibroblasts and subsequently cardiac myocytes in mice during pressure overload." (PMID 23372656, 2013). "Accordingly, Salio and colleagues reported that lack of PTX-3 reduced the number of capillaries in reperfused cardiac tissue, as well as induced a worse outcome in a study of cardiac ischemia." (PMID 29703251, 2018).
ovarian carcinoma (6 papers, 2020 to 2024). A malignant neoplasm originating from the surface ovarian epithelium. "The Cox proportional hazard model indicates that high PTX3 expression is an independent risk factor for the prognosis of ovarian epithelial cancer patients." (PMID 33952272, 2021). "Receiver operating characteristic (ROC) curves were carried out to further evaluate the diagnostic value of PTX-3 in ovarian epithelial cancer." (PMID 33952272, 2021). "Twenty-five genes were shared between the purple module and DEGs, 13 genes were related to the prognosis of ovarian epithelial cancer patients, and the PTX3 gene had the highest hazardous risk (HR) value." (PMID 33952272, 2021). "In conclusion, through WGCNA and a series of comprehensive bioinformatics analyses, PTX3 was first identified as a novel diagnostic and prognostic biomarker for ovarian epithelial cancer." (PMID 33952272, 2021). "To further verify the diagnostic and prognostic performance of the PTX-3 gene in an external GEO dataset, first, we selected two GEO datasets (including normal ovarian epithelial samples and ovarian epithelial cancer epithelial samples) to verify the diagnostic efficacy of PTX3." (PMID 33952272, 2021). "Their results proved that PTX-3 could be a useful diagnostic tool (with a cut-off index of >3.5 ng/mL) for mature cystic teratomas, one of the most common forms of ovarian cancer, as well as differentiating tools from endometriomas, which often present similar appearance on ultrasound scan." (PMID 36499628, 2022). "PTX3 may become a new diagnostic and prognostic marker of ovarian epithelial cancer." (PMID 33952272, 2021). "PTX3 may become a new diagnostic and prognostic marker of ovarian epithelial cancer in the future." (PMID 33952272, 2021). "Compared with the other 12 genes, PTX3 had the largest upregulation in ovarian epithelial cancer tissues." (PMID 33952272, 2021). "Immunohistochemical analysis was used to identify the expression level of Pentraxin 3 in ovarian epithelial cancer samples." (PMID 33952272, 2021). "In GSE9891, the PTX3 level was associated with the OS (HR = 1.92, p = 0.0052) and PFS (HR = 1.55, p = 0.0031) of ovarian epithelial cancer patients." (PMID 33952272, 2021). "First, due to the lack of in vitro or in vivo experiments, the in-depth mechanism of PTX3 in ovarian epithelial cancer needs to be further elucidated." (PMID 33952272, 2021). "After systematic analysis of ovarian cancer-related coexpression modules through a series of bioinformatics methods, PTX3 was confirmed to be a biological marker of ovarian epithelial cancer." (PMID 33952272, 2021). "In GSE66957 (12 normal ovarian epithelial samples, 57 ovarian epithelial tumor samples), the AUC value of PTX3 to predict ovarian epithelial cancer was 0.779 (p = 0.003)." (PMID 33952272, 2021). "In GSE26193, the PTX3 level was associated with the OS (HR = 1.79, p = 0.041) and PFS (HR = 1.72, p = 0.041) of ovarian epithelial cancer patients." (PMID 33952272, 2021). "Further protein level verification of PTX3 shows the clinical value in the diagnosis and prognosis of ovarian epithelial cancer." (PMID 33952272, 2021). "PTX3 was found to be overexpressed in ovarian epithelial cancer and related to the degree of differentiation." (PMID 33952272, 2021). "In conclusion, through WGCNA and a series of comprehensive bioinformatics analyses, PTX3 was first confirmed as a biomarker for ovarian epithelial cancer." (PMID 33952272, 2021).
ovarian carcinoma (continued). "Furthermore, the results of the analysis by the Kaplan–Meier (KM) method and single-factor and multifactor Cox analyses showed that PTX3 was an independent adverse prognostic factor in patients with ovarian epithelial cancer." (PMID 33952272, 2021). "A further subgroup analysis showed that higher PTX3 expression was associated with the poor prognosis of patients with high-grade ovarian epithelial cancer but was not related to the prognosis of patients with low-grade ovarian epithelial cancer." (PMID 33952272, 2021). "The results showed that PTX3 was highly expressed in ovarian epithelial cancer tissues." (PMID 33952272, 2021). "Finally, in GSE30161, the PTX3 level was also associated with the OS (HR = 2.93, p = 0.00095) and PFS (HR = 2.63, p = 0.0013) of ovarian epithelial cancer patients." (PMID 33952272, 2021). "In addition, we tried to analyze the diagnosis and prognostic value of PTX3 in patients with ovarian epithelial cancer." (PMID 33952272, 2021). "PTX3 has a higher hazardous risk (HR) value, and no previous studies have shown its relationship with ovarian epithelial cancer." (PMID 33952272, 2021). "However, the role of PTX3 in ovarian epithelial cancer is still unclear." (PMID 33952272, 2021).
periodontal disease (6 papers, 2012 to 2023). "The two recent clinical studies were published suggesting that PTX-3 in gingival crevicular fluid is considered a diagnostic marker of periodontal disease inflammatory activity." (PMID 22966213, 2012). "In a recent clinical work, PTX3 is suggested to associate with the severity of periodontal disease and considered as a marker of inflammatory activity in periodontal disease." (PMID 22966213, 2012). "Pentraxin-3, has also been suggested to be a key biomarker for periodontal disease diagnosis, which is supported by our previous findings that salivary levels of pentraxin-3 in combination with specific ASVs (belonging to Streptococcus sp., Selenomonas sp., and Treponema spp)." (PMID 35360114, 2022). "It is important to also consider that the increased concentration of PTX3 in these clinical studies might probably be related to the destructive periods in periodontal disease." (PMID 22966213, 2012). "In light of these observations, PTX-3 might probably play a role in the pathogenesis of periodontal disease." (PMID 22966213, 2012). "A high concentration of PTX3 in gingival crevicular fluid (GCF), saliva, and plasma correlates with the severity of periodontal disease, as defined by clinical evaluation parameters." (PMID 31744201, 2019).
psoriasis (6 papers, 2016 to 2025). An autoimmune condition characterized by red, well-delineated plaques with silvery scales that are usually on the extensor surfaces and scalp. "In this study, we observed elevated levels of inflammatory markers such as homocysteine, pentraxin 3, resistin, and leptin as well as a reduced levels of anti-inflammatory adiponectin in pediatric psoriasis patients compared to healthy controls." (PMID 40095687, 2025). "A Turkish study on 58 patients and an Italian study on 44 patients revealed significantly higher pentraxin 3 levels in psoriasis patients compared to controls." (PMID 40095687, 2025). "Pentraxin 3: Mean (±SD) 4.3 (1.4) pg/mL in the psoriasis group vs. 3.2 (0.9) pg/mL in the control group (p < 0.001, two-tailed; effect size = 0.17)." (PMID 40095687, 2025). "The whole blood GLUT 1 expression significantly increased in psoriatic patients and correlated positively with serum IL-6, fetuin-A, PTX3 levels and with the severity of psoriasis while negatively with serum PEDF levels." (PMID 38052851, 2023). "Its expression correlates with the severity of psoriasis, as well as with serum levels of IL-6, fetuin-A, and PTX3." (PMID 38052851, 2023). "As for the duration-based division, significance was observed in short-term psoriasis in which the total treatment resulted in a meaningful decrease in PTX3 concentration (p < 0.05)." (PMID 35888704, 2022). "In turn, duration-based division with the threshold of 20 years revealed that in patients with short-term psoriasis (<20 years), the pentraxin 3 level was significantly higher than in those with long-term disease (>20 years)." (PMID 35888704, 2022). "PASI-based division showed a significant decrease in PTX3 concentration in moderate-to-severe and severe psoriasis." (PMID 35888704, 2022). "In our study, PTX3 was positively correlated with CRP level which reflects that the protein acts as an indicator of inflammation in psoriasis." (PMID 35888704, 2022). "These outcomes point to the uncertain role of pentraxin 3 in the interrelations between inflammation and adipose tissue in psoriasis." (PMID 35888704, 2022). "The mean serum pentraxin 3 level was significantly higher in patients with psoriasis, compared to controls (p < 0.01)." (PMID 35888704, 2022). "The mean serum pentraxin 3 concentration in patients with psoriasis was 245 ± 34.2 pg/mL before treatment and 165 ± 18.1 pg/mL after, and it was significantly higher compared to the controls, who had a concentration of 136 ± 20.5 ng/mL (p < 0.01)." (PMID 35888704, 2022). "In our study, serum pentraxin 3 level was significantly higher in patients with psoriasis, compared to the healthy subjects." (PMID 35888704, 2022). "The implication of PTX3 in the innate immunity was studied, and levels of PTX3 are considered a marker of inflammation in psoriasis, as well." (PMID 27403446, 2016). "The aim of this study was to evaluate the inflammatory potential and the association of psoriasis with metabolic and cardiovascular risk by analyzing serum concentrations of homocysteine, adiponectin, resistin, leptin, and pentraxin 3 in pediatric patients with psoriasis." (PMID 40095687, 2025). "Elevated pentraxin 3 levels have been observed in adult psoriasis patients." (PMID 40095687, 2025). "Our study similarly found significantly elevated pentraxin 3 levels in the children with psoriasis." (PMID 40095687, 2025). "PTX-3 may participate in the pathogenesis of psoriasis and can indicate the disease activity of psoriasis." (PMID 39021820, 2024). "The current work aimed to investigate the whole blood GLUT1 mRNA expression and serum PEDF, IL-6, fetuin-A, and PTX3 levels in psoriatic patients and tested their correlations with the severity of psoriasis using the psoriasis area and severity index (PASI) score." (PMID 38052851, 2023). "PTX3 may serve as a protective protein regarding the development of cardiometabolic disorders, especially in overweight and obese patients with psoriasis." (PMID 35888704, 2022).
psoriasis (continued). "Furthermore, higher PTX3 levels were reported among patients with severe psoriasis, compared to those with mild psoriasis or healthy individuals." (PMID 35888704, 2022). "Moreover, we noted a statistically higher PTX3 level among patients with short-term psoriasis which suggests greater protection from oxidation among this group." (PMID 35888704, 2022). "However, the data on PTX3 and psoriasis are ambiguous as in another study the levels remained unchanged in patients with psoriatic arthritis." (PMID 35888704, 2022). "Therefore, we aimed to elucidate the potency of PON1 and PTX3, as they could be used as novel regulators of cardiometabolic disorders in psoriasis in terms of systemic therapy." (PMID 35888704, 2022). "Interestingly, statistically higher PTX3 levels in short-term psoriasis might reflect a greater protective impact of PTX3 in these patients, and perhaps in long-lasting psoriasis, other pro-inflammatory stimuli may enhance the ongoing metaflammation." (PMID 35888704, 2022). "Within the psoriatic group (G2), the Psoriasis Area and Severity Index (PASI) scores correlated positively with whole-blood GLUT1 mRNA fold changes and serum levels of IL-6, fetuin-A, and PTX3, and negatively with serum PEDF levels." (PMID 38052851, 2023). "Our findings highlight the significant role of PTX3 and PON1 in chronic inflammation and psoriasis severity." (PMID 35888704, 2022). "In severe psoriasis, significant negative correlations of pentraxin 3 level and RBC, Chol and TG were observed." (PMID 35888704, 2022). "Regarding PASI-based division, in patients with mild psoriasis, significant negative correlations between pentraxin 3 and PASI or PLT, and positive correlations with HGB were noted." (PMID 35888704, 2022). "However, although PTX3 does not seem to be related to CRP in psoriasis, it is reportedly positively related to the extent and severity of skin psoriasis." (PMID 28225768, 2017).
sarcoma (6 papers, 2015 to 2024). A usually aggressive malignant neoplasm of the soft tissue or bone. "The authors found that PTX3-deficient mice were susceptible to chemically induced sarcomas and skin carcinomas, presumably because inadequate control of complement activation increases carcinogenesis in affected tissues." (PMID 33167384, 2020). "Furthermore, genetic deficiency of PTX3 is associated with increased deposition of C3 on sarcoma cells, and administration of the exogenous protein abrogates this effect via FH-dependent mechanisms." (PMID 33324220, 2020). "In support of this, Bonavita and colleagues studied the role of pentraxin-3 (PTX3) in models of chemically induced sarcomas and skin carcinomas." (PMID 33167384, 2020). "Twice as many Ptx3−/− mice developed sarcomas compared to Ptx3+/+, and incidence and multiplicity of papillomas and progression to carcinomas were also much higher in Ptx3−/−than in Ptx3+/+." (PMID 26075183, 2015). "Carcinogenesis was investigated in Ptx3−/− and Ptx3+/+ mice treated with 3-methylcholantrene (3-MCA) or 7,12-dimethylbenz [α] anthracene/terephthalic acid (DMBA/TPA) to induce formation of sarcomas or papillomas/skin carcinomas, respectively." (PMID 26075183, 2015). "Elevated PTX3 plasma levels were related to poor prognosis in various cancers although not sarcoma." (PMID 31195680, 2019).